CPT1A (carnitine palmitoyltransferase 1A)
Diseases named in the same sentence as CPT1A in open-access papers (continued):
Sharing a sentence is not in itself a finding about the gene and the disease.
tumor (continued). "Together, these results highlight the heterogeneity of tumor cells from metabolic perspective, and identify PCK/CPT1A as a target for metabolic reprogramming and precision therapy of 18F-FDG-PET/CT-negative cancers." (PMID 41888524, 2026). "In CPT1A knockdown models, combined treatment with anti-PD-1 and butyrate restored CD8+ T cell infiltration and enhanced anti-tumor efficacy." (PMID 41278473, 2025). "Carnitine palmitoyltransferase 1A (CPT1A) inhibitors, like ST1326, have demonstrated early clinical success by weakening tumor cell survival under hypoxic and nutrient‐deprived conditions through fatty acid oxidation (FAO) inhibition." (PMID 40391753, 2025). "In this study, it is demonstrated that knockout of mutant FAT1 in HNSCC cells attenuates CPT1A‐driven fatty acid oxidation (FAO) through downregulation of the transcription factor ASCL2, leading to marked suppression of tumor growth." (PMID 40407216, 2025). "It is also anticipated that the tumor immunosuppressive milieu would be reversed by targeted intervention of important molecules involved in tumor lipid metabolism, such as CD36 and CPT1A." (PMID 41451233, 2025). "The combination of osimertinib and sitagliptin resulted in a greater reduction in GPF‐positive tumor cells and a concurrent decrease in DPP4, Nrf2, and CPT1A expression." (PMID 40479551, 2025). "Consistently, there were less Ki67 (cell proliferation marker) positive staining in tumor tissue from mice in sh-RACGAP1 group, which was enhanced after CPT1A overexpression." (PMID 41444950, 2025). "In murine models, inhibition of CPT1A with Etomoxir reduces MDSC infiltration and reverses their tumor-promoting activity." (PMID 41312365, 2025). "Traditional platinum drugs were modified to interact with CPT1A to inhibit FAO, thereby enhancing the anti-tumor effect of platinum drugs." (PMID 40290117, 2025). "Collectively, these observations argue that, while ketosis can exacerbate ErbB2+ tumor growth, combining it with FAO blockade via Cpt1a targeting is an effective therapeutic strategy." (PMID 39097623, 2024). "We confirmed that, while the recruitment of CD4+ T cells was unaffected, tumor-infiltrating CD8+ cytotoxic T cells and natural killer (NK) cells was significantly enriched by Cpt1a inhibition and 7.16.4 mAb treatment." (PMID 39097623, 2024). "Treatment of the carnitine palmitoyltransferase 1a (CPT1A)-specific inhibitor decreases the immunosuppressive function of MDSCs and enhances ferroptotic inducer-initiated tumor cell ferroptosis." (PMID 39596904, 2024). "Cpt1a ablation significantly decreased the basal, ATP synthesis-coupled and maximal oxygen consumption rates (OCR) of ErbB2+ tumor cells, indicating an overall suppression of respiration." (PMID 39097623, 2024). "Among patients with a tumour regression grade (TRG) score of 1, which indicates a minimal number of residual tumour cells, a high IHC score for CPT1A is often observed." (PMID 39607749, 2024). "The additive approach of combining Cpt1a inhibition with the ketogenic diet or anti-HER2 mAb therapy demonstrates promising results, including reduced tumor growth, proliferation, and metastasis." (PMID 39097623, 2024). "Since macrophages in the tumor microenvironment often exhibit an M2 phenotypic transition, which has been associated with tumor metastasis, we compared the total and M2 phenotypes of macrophages in primary tumors and lymph nodes with or without CPT1A inhibition." (PMID 38520724, 2024). "The GEPIA web tool was used to depict the expression levels of CPT1s, including CPT1A, CPT1B and CPT1C, among different tumor stages in the TCGA cohort to evaluate the correlation between tumor stage and CPT1s expression." (PMID 37078750, 2023). "A knockdown of carnitine palmitoyltransferase 1A (CPT1A), a critical enzyme in fatty acid oxidation (FAO), also reduced tumor growth and increased survival, according to in vivo studies." (PMID 37370767, 2023).
tumor (continued). "As a key rate-limiting enzyme for the intracellular transport of FAs to the mitochondrial matrix for FAO, carnitine palmitoyltransferase 1A (CPT1A) is highly expressed in various malignant tumors and promotes tumor progression." (PMID 37291333, 2023). "Further investigation into the mechanism of the lipid-lowering effects of ECD revealed that it downregulated ACSL4, ACSL1, CPT1A, and FASN levels in colorectal tissues and downregulated tumor formation in the colorectum." (PMID 37078067, 2023). "In contrast, overexpression of CPT1A in SUNE1 cells increased the growth and tumor weight in vivo compared with the control group." (PMID 35411000, 2022). "CPT1A dramatically affects the malignant phenotypes in NPC, including proliferation, anchorage-independent growth, and tumor formation ability in nude mice." (PMID 35411000, 2022). "In lung carcinoma and colon adenocarcinoma, etomoxir was shown to target CPT1A to inhibit FAO of MDSCs and reversed its tumor-promoting effects by abrogating the infiltration of MDSCs into the tumor." (PMID 36131916, 2022). "We injected B16 tumor–bearing mice with control, Stattic-treated (STAT3 inhibitor), etomoxir-treated (CPT1A inhibitor), or Fer-1–treated (ferroptosis inhibitor) Tc9 cells." (PMID 35192544, 2022). "Studies suggested that FAO is highly activated due to the upregulated expression of CPT1A in radiation-tolerant NPC cells, which supplies energy for the proliferation and progression of tumor cells." (PMID 34566954, 2021). "When the energy demand of tumor cells increases, peroxisome proliferator-activated receptor coactivator 1 (PGC-1α) can promote FAO in NPC cells via the CEBPB/CPT1A signalling axis to protect mitochondria from toxic lipid overload and resist radiation." (PMID 34566954, 2021). "The tumor-promoting effects of adipocytes and fatty acids were reported in CRC; adipocytes increased FAO in CRC cells via upregulating CPT1A, which links the adipocyte-mediated cellular metabolism to the Wnt signaling in CRC cells." (PMID 34200820, 2021). "The result showed the expressions of SOAT1 and CPT1A were mildly decreased under a ND condition, but dramatically increased under HFD condition in HCC tissues compared with the adjacent non-tumor tissues." (PMID 34052835, 2021). "In particular, the fatty acid metabolism related genes, such as FATP2, ACADL, CPT1A, and so on, were elevated in PTC specimens compared to that in para-tumor specimens." (PMID 34976793, 2021). "The results showed that GSK3β and GAD1 were significantly downregulated and CPT1A and PKM2 were upregulated in CSCC compared with NC samples (p < 0.05), indicating that the catabolism of sugar and lipids was enhanced in tumor cells." (PMID 31465717, 2020). "Previous studies examining the role of CPT1A in renal clear cells have observed that the HIF gene can directly target the CPT1A gene and subsequently suppress the development of the tumor by eliminating the deposited lipid." (PMID 33381539, 2020). "Therefore, one can posit that changes in CPT1A expression may not just be driven by specific mutations or other genomic events, but rather, are part of the broader alterations that occur during tumour initiation and progression." (PMID 30092766, 2018). "Reintroduction of CPT1A into VHL-defective cells not only reverses the lipid deposition phenotype, but importantly reduces tumor growth in vivo." (PMID 29176561, 2017). "The fact that the HER2+/PIK3CAmut cells exhibit a higher basal CPT1A activity and lower lipid droplet level is consistent with a heightened state of lipid utilization in these cells, which could potentially in concert with lipogenesis to facilitate tumor cell growth." (PMID 27563814, 2016). "Conversely, by gene array studies, a decreased expression was shown after CPT1A silencing of several factors, such as SERPINB2 and PDGF-A, related to cell survival and tumor progression." (PMID 26799588, 2016).
tumor (continued). "The expression of PLIN1 (p < 0.001), FABP4 (p = 0.029), CPT-1A (p = 0.001), ACOX-1 (p < 0.001), and FASN (p < 0.001) differed significantly among these tumor subtypes." (PMID 25751270, 2015). "To verify the anti-tumor effect of sh-RACGAP1 in vivo, we established xenograft tumor models by subcutaneously injecting MDA-MB-231 cells, and MDA-MB-231 cells transfected with NC, sh-RACGAP1 and sh-RACGAP1 + oe-CPT1A, respectively." (PMID 41444950, 2025). "Furthermore, immunofluorescence analysis of tumour tissues from tumour-bearing mice confirmed the coexpression of CXCR2, CPT1A, and CD47, supporting a functional connection between the IL-8/CXCR2 pathway and metabolic regulation." (PMID 41163221, 2025). "Coculture experiments revealed that CPT1A expression was markedly elevated in Huh7 cells when cultured with aHSCs, underscoring the metabolic influence tending to FAO exerted by aHSCs on tumor cells." (PMID 40365837, 2025). "Therefore, restoring CPT1A levels in RCC cell lines can reduce the number of LDs and inhibit tumor growth." (PMID 41421797, 2025). "CPT1A overexpression was also observed in CRC cells, and its inhibition by the treatment with a secolignan-type compound, 2,6-dihydroxypeperomin B (DHP-B), a compound isolated from the plant Peperomia dindygulensis, suppresses tumor growth and progression." (PMID 40361394, 2025). "High levels of CPT1A and increased FAO are crucial factors in tumor metastasis and drug resistance." (PMID 41293266, 2025). "This study highlights the crucial role of CPT1A-mediated MDSC ferroptosis resistance through SLC7A11 metabolic reprogramming and MDSCs’ immunosuppressive function via the ARG1 signaling pathway in persisting tumor immune evasion." (PMID 39596904, 2024). "Immunohistochemistry results revealed that CPT1A expression did not increase, while tumour cell proliferation factor Ki67 expression was significantly reduced." (PMID 38245554, 2024). "Targeting CPT1A, a critical enzyme in FAO, with inhibitors such as etomoxir and ranolazine, has been shown to reduce fatty acid transport into mitochondria, thereby suppressing tumor growth." (PMID 39456967, 2024). "In the absence of CPT1A knockdown, radiotherapy reduced the percentage of Ki67-positive cells in the xenograft tumours by 32.9% (approximately 39.6% of the pre-irradiation baseline)." (PMID 39607749, 2024). "This regulation of glucose and lipid transporters contributes to the enhanced sensitivity of tumor cells to the ketogenic diet and anti-ErbB2 mAb therapy in the absence of Cpt1a." (PMID 39097623, 2024). "In contrast, CPT1A, p-MEK and p-ERK expression decreased in tumour tissues." (PMID 38245554, 2024). "Nonetheless, the MCKD was not able to rescue tumor growth in vivo to the level of Cpt1a-proficient ErbB2+ tumor cells." (PMID 39097623, 2024). "In contrast to Cpt1a-proficient cells, low glucose conditions completely supressed the growth of tumor cells lacking Cpt1a." (PMID 39097623, 2024). "CPT1A regulates the expression and stability of its substrate proteins, such as S100A10 and enolase 1, through CPTase-independent lysine succinyltransferase activity, thereby promoting tumor cell growth, proliferation and migration." (PMID 37291333, 2023). "Myc-overexpressing triple-negative breast cancer (TNBC) has a greater bioenergetic dependence on FAO, and CPT1A can be pharmaceutically inhibited to reduce energy metabolism in Myc-overexpressing TNBC cells and stop tumor growth in a xenograft model of Myc-overexpressing TNBC." (PMID 37033619, 2023). "CPT1A and CD47 are highly expressed in radiotherapy resistant GBM tumors, and inhibition of CPT1A can result in decreased CD47 expression and increased macrophage phagocytosis of tumor cells." (PMID 37033619, 2023). "We observed that TAMs from mice reconstituted with Cpt1a-deficient bone marrows expressed lower levels of Cpt1a, and FGK45 treatments failed to suppress tumor growth and tumor burden." (PMID 36823405, 2023).
tumor (continued). "After knockdown of CPT1A or MFF, mitochondrial fusion is enhanced, and tumor cell growth is inhibited, partly because fused mitochondria might lead to the accumulation of damaged or senescent mitochondria in cells, which is not conducive to cell survival." (PMID 37291333, 2023). "Recent reports have indicated that pharmacologic inhibition of CPT1A and FAO could prevent ER-positive BC tumour growth and cell proliferation." (PMID 37803002, 2023). "We observed that metastatic burden was highly reduced in the absence of CPT1a expression compared to control, while primary tumor growth showed no changes (upon CPT1a knockdown) and a small reduction (upon CPT1a knockout) compared to control." (PMID 36732635, 2023). "Indeed, ET treatment or in CPT1A−/−, CPT2−/−, and ACAD9−/− cells, radiation-mediated elimination of the clonogenic tumor cells by 25–50%." (PMID 35314680, 2022). "Increased expression of CPT-1A shows a negative correlation (r ≥ 1, p < 0.0001) with abundance of tumour infiltrating lymphocytes (TILs)." (PMID 36180554, 2022). "ACLY, ACLS4, ACSL5, SCD1, FABP1, FABP6, and CPT1A were all found to be substantially expressed in tumor tissue, although CD36, FABP3, and FABP4 were not." (PMID 35625633, 2022). "Our further experiments showed that overexpression of CPT1A in CAFs could significantly enhance the invasion and metastasis of CRC tumors and increase tumor growth in vivo." (PMID 33528867, 2021). "When comparing expressions of lipid metabolism—related proteins among molecular subtypes, the expression of PLIN1 (p < 0.001), FABP4 (p = 0.029), CPT-1A (p = 0.001), ACOX-1 (p < 0.001), and FASN (p < 0.001) differed significantly among the different tumor subtypes." (PMID 25751270, 2015). "In addition, PD-1 signaling upregulates CPT1A expression, augmenting FAO and reinforcing the metabolic adaptability of Tregs.In terms of lipid synthesis, the sterol regulatory element-binding protein (SREBP) pathway is elevated in tumor-infiltrating Tregs." (PMID 41312365, 2025). "This metabolic reprogramming not only supports the energy requirements of tumor cells but also enhances their survival and invasive capabilities by regulating the activities of enzymes involved in lipid droplet formation, fatty acid oxidation, and synthesis (e.g., FASN, CPT1A)." (PMID 40717587, 2025). "Moreover, restoring ASCL2 or CPT1A expression in FAT1 KO SCC1 cells not only counteracted the reduction in cell proliferation and clonogenicity mediated by FAT1 KO, but also reversed the inhibition of tumor growth in an orthotopic mouse model." (PMID 40407216, 2025). "Interestingly, the ketogenic diet increased tumor size and decreased survival in mice bearing wild-type ErbB2+ tumors, consistent with the efficient use of lipids and ketone bodies as metabolic fuels for NIC/Cpt1a+/+ tumor cells in vitro and in vivo." (PMID 39097623, 2024). "mRNA levels of Ascl4 were not significantly different between groups, although there was a pattern of increased expression in tumours from C/C and HF/C animals, while levels of Cpt1a, Acad11 and Srebp1c were all significantly decreased in C/C and HF/C tumours relative to non-tumour tissues." (PMID 39203941, 2024). "In addition, IHC provided further support showing that depletion of TM7SF2 significantly decreased CPT1A protein expression, whereas upregulation of TM7SF2 significantly increased CPT1A protein expression in mouse tumor tissues compared to corresponding controls." (PMID 38693136, 2024). "However, whether blocking CPT1A could enhance IKE-induced MDSC ferroptosis and thereby inhibit tumor growth is still unclear." (PMID 39596904, 2024). "Our findings indicated that the tumor suppressor SDHC could repress fatty acid synthesis by decreasing the expression of ALDH3A2 and simultaneously promote FAO by upregulating the FAO-related enzymes ACOX1 and CPT1A through the PI3K/AKT signaling axes." (PMID 38844980, 2024).
tumor (continued). "However, whether blocking CPT1A could enhance ferroptosis inducer IKE-initiated MDSC actual ferroptotic death and thereby inhibit tumor growth is still unclear." (PMID 39596904, 2024). "Unlike the signalling pathways of the cancer hallmarks, the epigenetic pathways were mostly recruited by CPT-1A across all carcinomas regardless of the state of progression of the tumour, with only histone phosphorylation and chromatin remodelling being associated with advanced disease." (PMID 36180554, 2022). "Interestingly, we also observed an increase in tumor weight in animals injected with 22Rv1 CPT1A OE cells, although this difference was not statistically significant." (PMID 34944922, 2021). "In addition, CPT1A expression was increased in invasive tumor cells within the adipose tissue compared to tumors without direct contact with adipocytes." (PMID 32913185, 2020). "These could help to identify new markers beside mTOR activity characterisation—such as FASN, CPT1a, ACSS2—or find good mitochondrial function markers (e.g. TOM20, NRF1), and to assign the metabolic expression profile of tumours before starting treatments in patients." (PMID 30574020, 2018). "To assess the effects of restoring CPT1A levels in ccRCC cells, we infected RCC4 and 786-O cells with an adenovirus encoding a constitutively active form of rat CPT1A that is not inhibited by malonyl-CoA (called CPT1AM) and assessed changes to lipid deposition and tumor growth." (PMID 29176561, 2017). "However, whether TM7SF2 remodels lipid metabolism by mediating CPT1A and thus promotes tumor occurrence have not been unequivocally identified." (PMID 38693136, 2024). "Furthermore, qRT-PCR research revealed that tumor tissues had significantly higher FATP4 and CPT1A expression levels than neighboring non-cancerous tissues." (PMID 41310903, 2025). "In vitro genetic ablation of Cpt1a severely impaired NIC cell migration and invasion, as well as colonization of the lungs in vivo, suggesting further that the observed impact on metastasis was independent of differences in tumor burden." (PMID 39097623, 2024). "In this study, the high expression of CPT1A might not promote mitochondrial biogenesis but might maintain mitochondrial fission to promote mitochondrial function through MFF, which is beneficial to the rapid metabolism of tumor cells." (PMID 37291333, 2023).